ADH1B (alcohol dehydrogenase 1B (class I), beta polypeptide)
Diseases named in the same sentence as ADH1B in open-access papers (continued):
Sharing a sentence is not in itself a finding about the gene and the disease.
ovarian carcinoma (continued). "We first assessed the extent to which copy number and ADH1B mRNA expression are related in ovarian cancer patient samples." (PMID 29861857, 2018). "We treated SKOV3ip1 ovarian cancer cells with conditioned media from mesothelial cells, endothelial cells, macrophages, or fibroblasts and assessed their ADH1B expression." (PMID 29861857, 2018). "In summary, the findings of the present study demonstrate that ADH1B upregulation plays an important role in determining the infiltrative phenotype of ovarian cancer cells." (PMID 29861857, 2018). "Our study's findings demonstrate that ADH1B promotes several factors that further contribute to ovarian cancer progression." (PMID 29861857, 2018). "We discovered a novel mechanism by which ovarian cancer cells with ADH1B overexpression become more infiltrative and can more efficiently penetrate the mesothelial cell monolayer." (PMID 29861857, 2018). "In our previous study, we discovered that alcohol dehydrogenase 1B (ADH1B) is a promising molecular biomarker for predicting residual ovarian cancer." (PMID 29861857, 2018). "Next, we investigated the upstream mechanism that regulates ADH1B expression in ovarian cancer cells." (PMID 29861857, 2018). "The current study establishes that ADH1B also plays a crucial role in ovarian cancer cells achieving mesothelial clearance." (PMID 29861857, 2018). "The relationship between miR-BART7 and ADH1B is of interest due to the report of ADH1B as a potential source of chemoresistance in ovarian cancer." (PMID 25485872, 2014). "The negative associations for ovarian cancer subtypes and endometrial cancer remained after adjusting for smoking heaviness and in analyses based on the ADH1B variant only." (PMID 41398582, 2025). "ADH1B was also discovered to dramatically upregulate tumor cell adhesion and cell spreading, suggesting that it could improve the mesothelial clearance of ovarian cancer." (PMID 36950684, 2023). "Based on our research, there is reason to believe that ADH1B may be a potential treatment strategy with the regulation of macrophages and neutrophils for ovarian cancer." (PMID 35756990, 2022). "Nevertheless, the research on ADH1B and ovarian cancer are much less." (PMID 35756990, 2022). "Ovarian cancer patients with higher ADH1B expression have favorable OS and PPS." (PMID 35756990, 2022). "Hence, we conducted that ADH1B was allowed to function as a biomarker aiding in the treatment and prognosis of ovarian cancer." (PMID 35756990, 2022). "On this basis, ADH1B may be a potential therapeutic target and contribute to the treatment of ovarian cancer." (PMID 35756990, 2022). "High expression of ADH1B was correlated with a markedly higher risk of residual disease in OSC, which played a significant role in accelerating ovarian cancer cell infiltration and may have enhanced the possibility of postoperative residual lesions." (PMID 32880385, 2020). "Collectively, these findings indicate that ADH1B plays an important role in the pathways that promote ovarian cancer cell infiltration and may increase the likelihood of residual disease following surgery." (PMID 29861857, 2018). "We also discovered that hypoxia increases ADH1B expression in ovarian cancer cells." (PMID 29861857, 2018). "We then assessed the expression of ADH1B in ovarian cancer cell lines." (PMID 29861857, 2018). "The purpose of the present study was to determine the extent to which ADH1B has a functional role in ovarian cancer invasiveness, which may contribute to increased likelihood of leaving residual disease." (PMID 29861857, 2018). "However, specific and systemic studies on ADH‐1B in ovarian cancer still exhibit a large gap." (PMID 37605299, 2023). "Moreover, we analyzed the co-expressed genes of ADH1B and found that these genes positively or negatively correlated to ADH1B might have a considerable influence on prognosis and treatment of ovarian cancer." (PMID 35756990, 2022).
ovarian carcinoma (continued). "Consequently, ADH1B could be significant for immune infiltration and be valuable in guidelines for treatment and evaluation of prognosis in patients with ovarian cancer." (PMID 35756990, 2022). "It was concluded that ADH1B might provide a new perspective for the treatment of ovarian cancer." (PMID 35756990, 2022). "Furthermore, we identified the expression levels of ADH1B in ovarian cancer from several aspects." (PMID 35756990, 2022). "In addition, ADH1B has shown great importance in the immune microenvironment in ovarian cancer." (PMID 35756990, 2022). "We compared the ADH1B expression between ovarian cancer tissue and normal tissues in GSE18520 and GSE26712, and found the reduced ADH1B expression in tumor tissues." (PMID 35756990, 2022). "Similarly, our observations that single gene knockouts of ALDOB, ADH1B, NEU1, and NT5E block the metabolic alterations during both transitions concur with previous studies that show suppression of ovarian cancer growth upon silencing these genes." (PMID 37876796, 2023).
colorectal cancer (15 papers, 2012 to 2025). A primary or metastatic malignant neoplasm that affects the colon or rectum. "Several studies found that the ADH1B was associated with colorectal cancer and obesity, suggesting its potential role in multiple diseases." (PMID 37795758, 2023). "ADH1B is downregulated in colorectal cancer by myc, which is associated with hyperactivation of Wnt signaling." (PMID 36923554, 2022). "ADH1B mutations have also been extensively studied and have been associated with esophageal, head and neck, ovarian, and colorectal cancer." (PMID 33688464, 2021). "There were several meta-analyses focussed on ADH1B Arg47His polymorphism and only one particular type of cancer risk, such as esophageal, head and neck, gastric and colorectal cancer." (PMID 30872408, 2019). "Decreased expression of ADH1B gene has been proved to be associated with disease progression in human colorectal cancer." (PMID 26975198, 2016). "Furthermore, in that study, ADH1B is linked to progression of type 2 diabetes mellitus which is a risk factor for colorectal cancer." (PMID 36923554, 2022). "Besides ethanol, ADH1B is known to oxidize endogenous aliphatic alcohol such as retinol and lipid peroxidation products that are associated with the development of colorectal cancer." (PMID 36923554, 2022). "ADH1B has also been reported to suppress cell proliferation in pancreatic cancer and colorectal cancer." (PMID 39884577, 2025). "Moreover, single nucleotide polymorphisms (SNPs) in ADH1B have been correlated with esophageal square cell carcinoma (ESCC), colorectal cancer (CRC), and overall cancer." (PMID 37324256, 2023). "Accordingly, previous studies have commonly focused on ADH1B, ADH1C, ALDH2, CYP2E1, and MTHFR genotypes as modifiers of the association between alcohol consumption and risk of alcohol-related cancers, including colorectal cancer." (PMID 29464080, 2018). "ADH1B was shown to be downregulated in colorectal cancer and lung cancer." (PMID 28427185, 2017). "Previous studies have found that ADH1B Arg47His polymorphism was associated with the pathogenesis of cancers such as colorectal cancer and head and neck cancer, while no positive correlation was found in hepatocellular carcinoma and gastric cancer." (PMID 27450204, 2016). "In Korea, a case-control study of alcohol dehydrogenase 1B (ADH1B) (rs1229984) and aldehyde dehydrogenase 2 (ALDH2) (rs671), which are well-known genes that affect drinking behavior, and colorectal cancer was reported." (PMID 37641821, 2023). "In other words, ADH1B and ALDH2 genotypes can be candidates for consideration of personalized prevention of colorectal cancer by aspirin." (PMID 36923554, 2022). "ADH1B and ALDH2 genotypes can be the markers for the personalized prevention of colorectal cancer by aspirin." (PMID 36923554, 2022). "Significant downregulation of ADH1B, ADH1C, and RDHL mRNAs was seen for colorectal cancer samples." (PMID 37569466, 2023). "ADH1B, ADH1C, RDHL, and RDH5 mRNAs were decreased in colorectal cancer samples, and expression of ADH1B and ADH1C mRNAs decreased regarding progression from adenoma to early and more advanced colorectal cancer." (PMID 37569466, 2023). "SNPs from ADH1B and ALDH2 genes, included in alcohol metabolism pathway, were genotyped in 1694 CRC cases and 1851 matched controls from the Molecular Epidemiology of Colorectal Cancer study." (PMID 24282520, 2013). "Taken together, these studies suggest that ADH1B plays an important role in the development of colorectal cancer in the absence of ethanol, that may relate to the aspirin's efficacy observed in our study." (PMID 36923554, 2022).
gastric cancer (12 papers, 2016 to 2025). A primary or metastatic malignant neoplasm involving the stomach. "ADH1C is involved in tumor immune cell infiltration, and ADH1B is associated with increased risk of breast and gastric cancer." (PMID 41374967, 2025). "Several reports investigated the association between ADH1B (rs1229984) polymorphism and gastric cancers." (PMID 39063094, 2024). "Polymorphisms in ADH1B associated with the increased risk of gastric cancer." (PMID 34401075, 2021). "Besides their involvement in metabolizing exogenous substances through cytochrome P450 and drug metabolic pathways, ADH7, ALDH3A1, and ADH1B are also cross-genes with high connectivity within these pathways, indicating their potential use as diagnostic and prognostic biomarkers for gastric cancer." (PMID 39418180, 2024). "A recent prospective study assessed the association of ADH1B and ALDH2 polymorphisms with synchronous gastric cancers." (PMID 39063094, 2024). "Compared with normal tissues, ADAM12, CEP55, LRFN4, and INHBA were up-regulated in gastric cancer samples, while ADH1B, DPT, FAM107A, and LOC100506388 were downregulated." (PMID 34686626, 2021). "However, both the less active ADH1B*1 allele and inactive ALDH2*2 allele carriers demonstrated an increased risk of synchronous gastric cancers (OR, 1.77; 95% CI, 1.03–3.04)." (PMID 39063094, 2024). "UGT1A1, GPX3, ADH1B, and ADH4 can serve as cross pathway regulatory nodes and can be integrated into a “metabolic immune prognostic model” in the future to optimize precision treatment strategies for gastric cancer." (PMID 41031088, 2025). "These key genes (UGT1A1, ADH4, ADH1B, CYP19A1, and GPX3) are crucial for the construction of our gastric cancer (GC) prognostic model." (PMID 41031088, 2025).
coronary heart disease (11 papers, 2012 to 2024). "A large meta-analysis of 56 epidemiological studies identified the rs1229984 variant of ADH1B to carry a more favorable cardiovascular profile associated with a reduced risk of coronary heart disease." (PMID 38727290, 2024). "Alcohol consumption instrumented by rs1229984 in ADH1B was strongly or suggestively associated with higher odds of any stroke, coronary artery disease, peripheral artery disease, aortic valve stenosis, and abdominal aortic aneurysm (all P<0.05)." (PMID 32367730, 2020). "The reason why rs1229984 in ADH1B was strongly associated with coronary artery disease, whereas only a suggestive association was observed between the overall genetic instrument for alcohol consumption and coronary artery disease, is unclear." (PMID 32367730, 2020). "In particular, ADH1B has been shown to be robustly associated with alcohol consumption and has been used in MR analyses to explore the causal effect of alcohol consumption on coronary heart disease risk factors." (PMID 25192829, 2014). "A one-sample MR study including 261,991 European descents showed that the ADH1B-rs1229984 variant is associated with non-drinking and lower alcohol consumption had a reduced risk of coronary heart disease than those without the genetic variant." (PMID 39574800, 2024). "The meta-analysis demonstrated lower serum non-HDL-C levels and a lower risk of coronary heart disease in drinkers with the ADH1B*2 allele than in drinkers with the ADH1B*1/*1 genotype." (PMID 26284938, 2015). "Additionally, we report results on associations of variants in ADH1B and ADH1C with ischemic heart disease and stroke in the context of a meta-analysis of previously published prospective studies published up to November 2011." (PMID 22363810, 2012).
esophageal squamous cell carcinoma (11 papers, 2013 to 2024). Esophageal squamous cell carcinoma (ESCC) is a type of esophageal carcinoma (EC) that can affect any part of the esophagus, but is usually located in the upper or middle third. "The JEC study confirmed that slow‐metabolizing ADH1B was a predictor of the development of metachronous esophageal SCC after ER and inactive ALDH2 was also associated with the development of metachronous esophageal SCC." (PMID 37409321, 2023). "Meta‐analysis also shows that heavy drinkers with slow‐metabolizing ADH1B are at a higher risk of developing esophageal SCC." (PMID 37409321, 2023). "It has also been reported that inactive ALDH2*1/*2 and less-active ADH1B*1/*1, and smoking, are risk factors for esophageal SCC." (PMID 23667679, 2013). "Particularly, an increased risk for esophageal squamous cell carcinoma (ESCC) in association with the ADH1B rs1229984 variant." (PMID 39574800, 2024). "Similarly, in West Asian countries such as Iran and Turkey, where esophageal squamous cell carcinoma (ESCC) diagnoses are comparatively high, a corresponding high frequency of the ADH1B*47His allele is found." (PMID 29166882, 2017). "A previous genome‐wide association study identified two novel esophageal squamous cell carcinoma (ESCC) susceptibility genes, ADH1B and ALDH2." (PMID 27038040, 2016). "In this study, we selected superficial esophageal SCC cases treated with ESD, and performed a replication study to confirm the relationship between ESCC and the ADH1B & ALDH2 risk alleles by using an Invader assay." (PMID 27038040, 2016). "Not only alcohol and smoking but also genetic factors such as aldehyde dehydrogenase 2 (ALDH2) and alcohol dehydrogenase 1B (ADH1B) have been identified as risks for esophageal squamous cell carcinoma (ESCC)." (PMID 29285315, 2017). "On multivariate analysis, slow‐metabolizing ADH1B (hazard ratio [HR] 2.21; 95% confidence interval [CI] 1.1–4.45) and inactive ALDH2 (HR 3.28; 95% CI 1.28–11.15) were significant predictors of the development of metachronous esophageal SCC or head and neck SCC." (PMID 37409321, 2023).
head and neck cancer (11 papers, 2016 to 2025). A primary or metastatic malignant neoplasm affecting the head and neck. "For instance, polymorphisms in the ADH1B gene, such as rs1229984, have been shown to correlate with a reduced risk of head and neck cancer." (PMID 40296873, 2025). "Individual with the fast ADH1B genotype, the head and neck cancer risk associated with drinking alcohol was raised as compared with those with the slow/nonfunctional ALDH2 genotypes." (PMID 35670037, 2023). "Polymorphisms of ADH1B have been associated with decreased risk of head and neck cancer in patients of Asian descent." (PMID 34648530, 2021). "For ADH1B‐rs1229984, a meta‐analysis of case‐control studies involving mainly East Asian populations showed that both AG and AA genotypes were associated with reduced risks of oesophageal cancer (9117 cases, 23 studies) and head and neck cancer (6646 cases, 16 studies) compared to GG genotype." (PMID 35048370, 2022). "In concordance with our results, earlier studies came to a comparable conclusion, as downregulation of ADH1B might have a role in multiple cancers, including colon, lung or head and neck cancer." (PMID 33807717, 2021). "Nonsynonymous SNPs in ADH1B (rs671) and ALDH2 (rs1229984) and head and neck cancer, oro‐/hypopharyngeal cancer and oral squamous cell carcinoma in univariate analysis." (PMID 37706329, 2023). "Nevertheless, in another study, head and neck cancer patients with the fast ADH1B and the slow/nonfunctional ALDH2 genotypes had the poorest overall survival." (PMID 35670037, 2023). "For ADH1B‐rs1229984, the HRs of AG and AA vs GG genotype were 0.80 (0.69‐0.93) and 0.75 (0.64‐0.87) for IARC alcohol‐related cancers, 0.61 (0.39‐0.96) and 0.61 (0.39‐0.94) for head and neck cancer (n = 196) and 0.68 (0.53‐0.88) and 0.60 (0.46‐0.78) for oesophageal cancer (n = 546)." (PMID 35048370, 2022).